JAK3 (Janus kinase 3)
Diseases named in the same sentence as JAK3 in open-access papers (continued):
Sharing a sentence is not in itself a finding about the gene and the disease.
X-linked SCID (4 papers, 2014 to 2023). "The phenotype of human SCID due to JAK3 mutations is very similar to that observed in X-linked SCID (X-SCID) resulting from mutations in the IL2Rγc-chain." (PMID 36291730, 2022). "At variance with X-linked SCID and JAK3 deficiency, where B cells are genetically impaired in their capacity to respond to IL-21 and differentiate into antibody-secreting cells, IL7R-deficient B cells are functional, as long as T cell help is provided." (PMID 31440487, 2019). "Similar to γc chain-deficient X-linked SCID, deficiency of JAK3 is known to cause autosomal recessive SCID with a reduced number of T-cells and natural killer cells as well as dysfunctional B-cells in normal cell count (T−B+NK− SCID) and hypogammaglobulinemia." (PMID 25205547, 2014). "Overall survival for patients with RAG deficiency was comparable to that observed for patients with X-linked SCID and JAK3 deficiency and use of conditioning regimen was not identified as an independent contributor to overall survival." (PMID 31440487, 2019).
acute leukemia (3 papers, 2013 to 2025). A clonal (malignant) hematopoietic disorder with an acute onset, affecting the bone marrow and the peripheral blood. "JAK1 and JAK3 mutations were also found in human acute leukemias and solid cancers." (PMID 23704931, 2013). "Co-mutations varied by subtype; MDS/MPN, NOS, and CMML cases frequently harbored mutations in epigenetic regulators (ASXL1, TET2) and splicing factors (SF3B1, SRSF2, ZRSR2), while acute leukemia cases showed alterations in JAK3, STAT3, and NRAS." (PMID 40806796, 2025). "In the acute leukemia group, CSF3R mutations co-occurred with alterations in signaling pathway genes, including JAK3, STAT3, and NRAS." (PMID 40806796, 2025).
allergic asthma (3 papers, 2017 to 2024). A asthma with a basis in a pathological type I hypersensitivity reaction. "Subsequent in vitro experiments emphasized the involvement of M2 macrophages in driving airway inflammation and triggering allergic asthma via the JAK3/STAT5/Fra-2 pathway." (PMID 39000247, 2024). "They developed a mouse model to study allergic asthma and demonstrated the activation of Fra-2 via the Janus kinase 3/signal transducer and activator of transcription 5 (JAK3/STAT5) pathway, contributing to its high expression." (PMID 39000247, 2024).
atherosclerosis (3 papers, 2015 to 2022). A disease characterized by the build-up of fatty material and calcium deposition in the arterial wall resulting in partial or complete occlusion of the arterial lumen. "Taking into account all these considerations, the main purpose of this study was to determine, for the first time whether JAK3 gene variants in RA patients are associated with the presence of subclinical atherosclerosis and CV events." (PMID 25815310, 2015). "Our immune cell restriction analysis findings show that JAK3 expression is highly correlated with T-follicular helper CD4+T cells, which stimulate atherosclerosis and additional CVDs." (PMID 35844366, 2022).
B cell lymphoma (3 papers, 2021 to 2023). "Several polymorphisms and mutation hotspots, such as 15 bp insertion (ins15) that encodes a Janus Kinase 3 (JAK3) motif and the number of 33 bp repeats were associated to specific variants, as well as B cell lymphomas and AIDS-associated B cell lymphomas in specific populations." (PMID 37781191, 2023). "Bruton’s tyrosine kinase (BTK) and Janus kinase 3 (JAK3) are popular synergistic targets for B-cell lymphoma." (PMID 37894618, 2023). "As JAK1 and JAK2 modulate epigenetic regulation of gene transcription through tyrosine phosphorylation of the histone protein H3 in leukemic- and B cell lymphoma- cell lines, we performed in vitro kinase assays to address whether JAK3 was also able to phosphorylate Histone H3." (PMID 33466582, 2021). "For instance, Bruton’s tyrosine kinase (BTK) and Janus kinase 3 (JAK3) are two validated and therapeutically amenable targets to effectively treat B-cell lymphomas and can be used to develop a dual-target inhibitor." (PMID 37894618, 2023).
bladder cancer (3 papers, 2011 to 2023). "We have also identified the activation of ERK1/2, p38MAPK, JNK, JAK1, JAK2, JAK3, Stat1, Stat2, and Stat3 in bladder cancer cells." (PMID 22962576, 2012). "Binding of IL-28A to IL-28AR1 induced the activation of ERK1/2, p38MAPK, and Jak/Stat (Jak2, Jak3, Stat1, Stat3, and Stat5) signaling pathways in bladder cancer cells." (PMID 22962576, 2012). "Another significant gene in this category, JAK3, is involved in the JAK-STAT signalling pathway, reported to be methylated in bladder cancer." (PMID 37245006, 2023). "Our results from bladder cancer cells indicate that IL-20 induced activation of ERK1/2 and Jak1, Jak2, Jak3, Stat1, Stat2, and Stat5." (PMID 22962576, 2012).
Cognitive impairment (3 papers, 2022 to 2024). Abnormal cognition is characterized by deficits in thinking, reasoning, or remembering. "Studies have shown that high-fat diet-induced cognitive impairment in mice is associated with intestinal Janus kinase-3 deficiency." (PMID 39036641, 2024). "A deficiency of Jak3 (Jak3-KO), however, resulted in a significant increase in the corresponding parameters, suggesting that the deficiency of Jak3 results in cognitive impairment, particularly with respect to the spatial cognition task." (PMID 36145091, 2022). "The current study extended those findings by proving an essential role of IEC-Jak3 in cognitive impairment, where impairment of intestinal Jak3 signaling acted as the source of brain inflammation through increased TLR signaling." (PMID 36145091, 2022). "As with the global Jak3-KO, we assessed the four parameters of cognitive impairment in IEC-Jak3-KO mice, viz., WME, RME, EBCC and RWME, using automated elevated radial arm maze in intestinal epithelial-specific Jak3-KO mice and their littermate controls." (PMID 36145091, 2022). "Since IEC deficiency of Jak3 impacted the cognitive impairment and brain deposition of pTau and Abeta, we determined whether IEC-Jak3 also impacted the TREM2 functions in the brain." (PMID 36145091, 2022). "Our data suggested the mice with impaired Jak3 signaling not only had a significant increase in cognitive impairment parameters, particularly related to working memory and roaming memory, but these increases were also associated with increased deposition of β-amyloid and pTau in the brain." (PMID 36145091, 2022). "However, the roles of non-receptor tyrosine kinase in general and Jak3 in particular in the gut-dysbiosis-mediated cognitive impairment were not known." (PMID 36145091, 2022).
colorectal cancer (3 papers, 2017 to 2024). A primary or metastatic malignant neoplasm that affects the colon or rectum. "Mutations were rare in JAK3; a Q39 frameshift occurred 20 times, with 6 of those in colorectal cancer (CRC)." (PMID 29121062, 2017). "Additionally, inhibiting JAK3/STAT3 in colorectal cancer cells promoted apoptosis and inhibited cell proliferation, aligning with previous results." (PMID 38579174, 2024). "The substance G4: ZM449829, a Jak3 inhibitor that failed to give cytotoxic effects in the 3D colorectal cancer model, may lead to immunosuppression due to reduced T cell proliferation." (PMID 31906582, 2020).
fatty liver (3 papers, 2021 to 2023). "Among them, JAK3 may be the one causing fatty liver in IARS1V79L mice, as its knockout is known to cause fatty liver in mice." (PMID 37108118, 2023). "Mice lacking janus kinase 3 (JAK3) exhibit metabolic disorders such as insulin resistance, weight gain, increased fasting insulin and glucose levels, decreased glucose tolerance, and hepatic steatosis." (PMID 36439174, 2022).
hair loss (3 papers, 2019 to 2024). "The results of the study are similar to those reported in clinical studies that CMX and brevilin A promote hair regrowth as JAK3 inhibitors in patients with hair loss." (PMID 37367071, 2023).
Hypertension (3 papers, 2022 to 2025). The presence of chronic increased pressure in the systemic arterial system. "IL6 can influence the development of Ang II-mediated hypertension by intervening the JAK2/JAK3 pathway." (PMID 35360657, 2022). "The VIMP results identified other potential associations that will not be able to be confirmed until new clinical evidence is published, e.g., the association between hypertension and JAK family kinases including JAK2 and JAK3." (PMID 35896580, 2022). "Ibrutinib-specific off-targets LCK, JAK3, and FLT3 were predicted to trigger inflammation processes related to hypertension; ERBB2, BLK, SRC, and CSK were predicted to trigger oxidative stress and endothelial dysfunction; and CSK were predicted to trigger the RAAS overactivation." (PMID 40744952, 2025).
hypogammaglobulinemia (3 papers, 2014 to 2021). "Hypomorphic mutations in other IEI genes (BTK, GATA2, IL2RG, JAK3, RAG1, RAG2, etc.)have been previously found in patients with antibody deficiency and milder phenotypes or in CVID patients." (PMID 34975878, 2021). "Our data revealed that the patient’s hypogammaglobulinemia is associated with CTLA-4 haploinsufficiency, increased JAK3 activity, and increased percentages of circulating CD4+ and CD8+ effector memory T cells." (PMID 29375547, 2017).
inflammatory skin disease (3 papers, 2016 to 2023). Inflammatory skin disorders covers a broad category that includes many conditions ranging in severity, from mild itching to grave medical health complications These disorders are common in people of all ages and races. "This suggests that selective JAK3 inhibition is the most promising approach for topical application in inflammatory skin diseases, as it can directly reverse the JAK profile of keratinocytes." (PMID 37624299, 2023).
lymphoproliferative disorder (3 papers, 2010 to 2024). "The transplantation of mouse bone marrow cells overexpressing human JAK3 A572V into lethally irradiated mice produced a lymphoproliferative disorder with megakaryocytic hyperplasia." (PMID 38474223, 2024). "In addition, persistently-activated JAK3 was reported in various cell lines that were derived from lymphoproliferative disorders, including mantle-cell lymphoma, Burkitt lymphoma, and anaplastic large-cell lymphoma." (PMID 20149240, 2010). "Taken together, small molecule inhibitors that can selectively block JAK3 activity may have enormous therapeutic value in several immune-related diseases including organ allograft rejection, as well as in lymphoproliferative disorders with aberrant JAK3 activation." (PMID 20149240, 2010).
nasopharyngeal carcinoma (3 papers, 2018 to 2024). A carcinoma arising from the nasopharyngeal epithelium. "PD-L1 was also induced by latent membrane protein-1 in Epstein–Barr virus (EBV)-associated nasopharyngeal carcinomas (NPC) through JAK3/STAT3 activation." (PMID 29765155, 2018).
osteoarthritis (3 papers, 2023 to 2025). A noninflammatory degenerative joint disease occurring chiefly in older persons, characterized by degeneration of the articular cartilage, hypertrophy of bone at the margins and changes in the synovial membrane. "For example, Green’s group illustrated that tRF-3003a, produced by the cleavage of tRNA-CysGCA, confers gene silencing of Janus Kinase 3 (JAK3) via AGO/RISC formation in osteoarthritis chondrocytes." (PMID 40565284, 2025). "For example, Green’s group detailed that tRF-3003a (derived from tRNACysGCA) confers gene silencing of Janus Kinase 3 (JAK3) by ‘seed sequence’ complementarity in osteoarthritis chondrocytes." (PMID 36761955, 2023).
renal cell carcinoma (3 papers, 2012 to 2018). "In order to confirm our in vitro data, IL-2Rβ chain, γc chain and JAK3 immunohistochemical stainings were performed on normal and tumor sections of nephrectomized kidneys with renal cell carcinoma." (PMID 22363690, 2012). "Several studies described defects in different components of the IL-2R signaling pathway, resulting in decreased T cell proliferation, such as the absence of CD25 expression, impaired STAT1 and STAT5 activation or soluble products released from renal cell carcinoma that suppress JAK3." (PMID 29342108, 2018).
retinal degeneration (3 papers, 2011 to 2017). Degeneration of the retina. "A strong induction of JAK3 mRNA levels suggested that JAK3 plays a prominent role in rd1 mouse retinal degeneration." (PMID 28404878, 2017). "JAK3, which is reported to be primarily expressed in immune-cells, is prominently increased at P14 (5-fold) of rd1 mice; it suggests that JAK3 is involved in the development of retina degeneration." (PMID 28404878, 2017). "Jak3, a proinflammatory gene expressed by immune cells and activated by interleukin receptors, is regulated by inflammation and tissue damage in the retina in models of photic damage and retinal degeneration." (PMID 21575160, 2011). "LIF signaling during retinal degeneration is thought to act through the JAK/STAT pathway including activation of Janus activated kinase 2 (JAK2), JAK3 and signal transducers and activators of transcription 3 (STAT3)." (PMID 23372671, 2013).
rheumatic diseases (3 papers, 2024 to 2025). "JAKi, with varying selectivity for JAK1, JAK2, JAK3, and Tyk2, have then the role of disrupting proinflammatory cytokine cascades in rheumatic diseases." (PMID 38554250, 2024). "The three drugs that are routinely used and discussed in rheumatic diseases are tofacitinib (TOFA; works on JAK families in this order- JAK3 > JAK2 > JAK1), baricitinib (BARI; JAK1, JAK2, and TYK2), and upadacitinib (UPA; JAK1 > JAK2 and JAK3)." (PMID 40282506, 2025).
stomach adenocarcinoma (3 papers, 2020 to 2024). "In addition, RNA sequencing (RNA-seq) of the transcriptome revealed that TYK2 and JAK3 mRNA levels were significantly increased in stomach adenocarcinoma, and both proteins were found to be prognostic biomarkers." (PMID 34439323, 2021). "Using an RNA-seq bioinformatics approach to compare stomach adenocarcinoma and normal tissues, TYK2 and JAK3 mRNA expression were positively associated with tumor grade, stage, and lymph node metastasis status, and patients with high TYK2 expression in their tumors had shorter overall survival." (PMID 34439323, 2021).
Stroke (3 papers, 2017 to 2025). Sudden impairment of blood flow to a part of the brain due to occlusion or rupture of an artery to the brain. "Future studies should investigate the effects of decernotinib in stroke models associated with reperfusion as well as the impact of JAK3 inhibition on long-term outcomes in embolic stroke models with and without thrombolysis with recombinant tissue plasminogen activator." (PMID 28790974, 2017). "Our findings indicate that the upregulation of Ptgs2, Lgals3, Il6r, and Jak3 further enhances the inflammatory response following stroke." (PMID 39847586, 2025). "JAK3 inhibition with decernotinib is also ineffective at reducing sensorimotor deficits after stroke." (PMID 28790974, 2017). "We found for the first time that total and phosphorylated/activated JAK3 are dramatically increased after stroke in the ipsilateral hemisphere (**P < 0.01; n = 5–13/group) in addition to increased IL-21 expression after stroke (**P < 0.01; n = 5–7/group)." (PMID 28790974, 2017). "The functional role of increased JAK3 activation after stroke remains to be further investigated." (PMID 28790974, 2017). "To study the potential role of JAK3 in stroke-induced neuroinflammation, we subjected mice to permanent middle cerebral artery occlusion and investigated the effects of JAK3 inhibition with decernotinib (VX-509) on infarct size, behavior, and levels of several inflammatory mediators." (PMID 28790974, 2017). "Previous stroke studies have shown that blocking T-cell infiltration is protective in stroke, and JAK3 KO mice have non-functional T-cells, so if JAK3 inhibition was neuroprotective, it would most likely be due to its effect on T-cells." (PMID 28790974, 2017). "In the same vein, JAK3 inhibition with 10 mg/kg decernotinib did not affect stroke-induced upregulation of Ccl2, Cxcl10, and Cxcl1, chemokines important for immune cell trafficking, nor proinflammatory mediators IL-1β, IL-6, Tnfα, Ptgs2, and Mmp-9 that exacerbate stroke damage." (PMID 28790974, 2017). "The major finding of this study is that JAK3 inhibition fails to protect the brain after stroke." (PMID 28790974, 2017). "Decernotinib did not alter stroke-induced total JAK3 levels." (PMID 28790974, 2017). "Although it is able to reduce the stroke-induced increase in pJAK3 and STAT3, downstream effectors of JAK3 activation, decernotinib is not neuroprotective in the acute phase of ischemic stroke." (PMID 28790974, 2017).
T-cell neoplasms (3 papers, 2019 to 2022). "JAK3 mutations have been reported in mainly T-cell neoplasms (29,), immunodeficiency syndromes, and B-cell neoplasms." (PMID 35111674, 2021). "Mutations of genes encoding for components of the JAK/STAT pathway are frequently found in T-cell neoplasms (predominantly mutations of JAK3, STAT3, and STAT5B)." (PMID 31766351, 2019). "Moreover, activating STAT5B mutations have been identified in a variety of hematological neoplasms, being identified as likely driver mutations in various T cell neoplasms, with JAK3 and STAT5B in the same mutation cluster in ALL." (PMID 35622134, 2022).
Thrombocytopenia (3 papers, 2023 to 2025). A reduction in the number of circulating thrombocytes. "The patient who died had multiple high-risk features (severe thrombocytopenia and elevated fetal hemoglobin) and acquired additional somatic mutations that included JAK3, TERT, KRAS, and CBL, and eventual transformation to AML." (PMID 39123476, 2024).
tuberculosis (3 papers, 2022 to 2024). A chronic, recurrent infection caused by the bacterium Mycobacterium tuberculosis. "Furthermore, tuberculosis reactivation via the “awakening” of dormant Mycobacterium tuberculosis has been linked to use of the JAK3/2 inhibitor tofacitinib." (PMID 36059986, 2022).
viral infections (3 papers, 2012 to 2024). "This underscores the complexity of alternative splicing of TLR4 and JAK3 and its potential significance in the context of viral infections." (PMID 38414855, 2024). "We presume that patients with severe viral infection may benefit from the treatment with selective JAK3 inhibitors that modulate the dysregulation of cytokine-mediated inflammation but allow T cell proliferation for the adaptive immune response against pathogens." (PMID 22359619, 2012).
adult T-cell leukemia/lymphoma (2 papers, 2021 to 2023). A peripheral (mature) T-cell neoplasm linked to the human T-cell leukemia virus type 1 (HTLV-1), adult T-cell leukemia/lymphoma is endemic in several regions of the world, in particular Japan, the Caribbean, and parts of Central Africa. "In adult T-cell leukemia/lymphoma (ATL), JAK3 FERM domain mutations have been shown to induce gain of function in JAK3 and to activate JAK3 in vitro." (PMID 33672930, 2021).
Alzheimer disease (2 papers, 2020 to 2024). A progressive, neurodegenerative disease characterized by loss of function and death of nerve cells in several areas of the brain leading to loss of cognitive function such as memory and language. "This variation underscores CD69’s role in immune modulation, from influencing regulatory T cell differentiation via the Jak3/Stat5 pathway to its association with Alzheimer’s disease pathology." (PMID 38742110, 2024). "The genes represented by the age‐DMRs included a few notable members such as Cyp46a1 and Abca7, which are involved in cholesterol metabolism and implicated in Alzheimer's disease, and few members of the WNT signaling and mesenchyme developmental pathways (e.g., Fzd1, Fzd8, Wnt5a, Jak3, Ptk7, Nrp2)." (PMID 32790008, 2020).